RUNX2 (RUNX family transcription factor 2)
Diseases named in the same sentence as RUNX2 in open-access papers (continued):
Sharing a sentence is not in itself a finding about the gene and the disease.
melanoma (continued). "In fact, our data indicate that RUNX2 induces the expression of CXCR4, which in turn promotes autophagy, cell invasiveness, and osteotropism, by inhibiting the mTOR signalling pathway in melanoma cells." (PMID 38474372, 2024). "Moreover, animal studies could be pursued, in order to test if the transplantation of RUNX2 KO melanoma cells into mice would lower the rates of tumour progression and metastasis, in comparison with the transplantation of homologous wild-type cells into identical models." (PMID 38474372, 2024). "In the present work, we succeeded in demonstrating the involvement of RUNX2 and CXCR4 in multiple stages of the pathophysiology of melanoma progression and metastasis." (PMID 38474372, 2024). "In this study, we aimed to investigate the role of RUNX2 and CXCR4 in melanoma, using in vitro cell cultures." (PMID 38474372, 2024). "These two approaches would provide proof-of-principle data strengthening the value of RUNX2 and CXCR4 as potential therapeutic targets against melanoma." (PMID 38474372, 2024). "After demonstrating the effect of RUNX2 on the expression levels of CXCR4, we sought to assess CXCR4’s impact on the formation of melanoma metastasis in the bone." (PMID 38474372, 2024). "It is important to note that the CXCL12/CXCR4 axis activates the AKT and ERK cell signalling pathways, and we have recently demonstrated that a reciprocal activation between the RUNX2 and AKT/ERK pathways occurs in melanoma." (PMID 38474372, 2024). "Our findings demonstrated that RUNX2 expression increased the protein levels of the LC3 and beclin autophagy markers in melanoma cells." (PMID 38474372, 2024). "The expression of RUNX2, MMP13 and CXCR4 at the protein level was also verified in the same melanoma cell lines." (PMID 38474372, 2024). "Thus, we tested if the expression of RUNX2 in melanoma cells could modulate this process." (PMID 38474372, 2024). "RUNX2 has been previously identified as a driver of epithelial to mesenchymal transition (EMT) processes and phenotype switching in melanoma." (PMID 36894939, 2023). "In particular, we used these melanoma cells because, differing only in the RUNT domain, they represent an useful model to evaluate the role of RUNX2 in the degradation processes by the proteasome." (PMID 37199076, 2023). "For the first time in melanoma, we also observed interaction and reciprocal activation between RUNT/RUNX2 and AKT/ERK signaling." (PMID 32204402, 2020). "As PTHrP expression is regulated by RUNX2, we measured PTHrP levels in WT and RUNT-KO melanoma cell culture media." (PMID 32204402, 2020). "By using the CRISPR/Cas9 technology, we partially deleted the RUNT domain or knocked out the whole RUNX2 gene containing the RUNT domain in A375 and MELHO melanoma cells." (PMID 32204402, 2020). "In a melanoma cell model with RUNT-deleted cells by CRISPR/Cas9 technique, a reduced cell proliferation, increased apoptosis, and reduced EMT traits, indicating RUNX2 as a likely therapeutic target, were reported." (PMID 31781477, 2019). "Indeed, the mutant Runx2 protein in 3G8 cells could still alter gene expression through indirect mechanisms, which are still relevant in understanding the role that Runx2 plays in melanoma." (PMID 31142788, 2019). "In this study, we focused on how RUNX2 acts by deleting its RUNT domain using CRISPR/Cas9 and then analyzing possible changes in melanoma cells." (PMID 30463392, 2018). "To confirm the mRNA expression results, we performed an immunohistochemical analysis of RUNX2 and AXL in the same melanoma tissue microarray (TMA)." (PMID 27102439, 2016). "We demonstrated the co-expression of RUNX2 with IGF-1R, EGF-R, PDGFRβ and AXL using ShRNA RUNX2-expressing melanoma cells and showed co-expression of RUNX2 with AXL in human melanoma samples." (PMID 27102439, 2016).
melanoma (continued). "In differentiation-supported conditions, TAFH RNAi-treated melanoma cells started to express chondrogenic-specific SOX9, NKX3.2 and RUNX2; adipogenic PPARG; and neurogenic NTRK2, NF-M and SYP mRNAs at 48 h post-stimulation of differentiation." (PMID 27499390, 2016). "We show that when the five PRT lines derived from the PLX4720-resistant 1205LU melanoma xenografts are treated in vitro with PLX4720, all PRT lines exhibit an increased RUNX2 expression (isoforms 2/3) as compared with vehicle-treated cells." (PMID 27102439, 2016). "Therefore, also in melanoma, RUNX2 could regulate the PI3K/AKT pathway through FAK up-regulation." (PMID 26204939, 2015). "Our results may, in part, highlight the role of RUNX2 in EFF CD8+CD226+ immunosurveillance at the epithelial barriers, as previously reported in melanoma." (PMID 39777847, 2025). "Additionally, in melanoma, it was shown that RUNX2 silencing led to decreased ITGBL1 expression, emphasizing the importance of RUNX2 in regulating ITGBL1 in different cancer types." (PMID 40287769, 2025). "In this system, the quantification of melanoma cell adherence to osteoblasts confirms their decreased infiltration level in the absence of RUNX2 or under CXCR4 inhibition." (PMID 38474372, 2024). "RUNX2 reactivates PI3K/AKT pathways, providing the high metastatic potential to melanoma cells." (PMID 35996134, 2022). "In melanoma cells, the RUNT domain of RUNX2 increases cell proliferation and migration." (PMID 32204402, 2020). "Cell spreading and metastases formation was monitored between the 5th (7 dpf) and 7th (9 dpf) day after the injection of RUNX2-expressing melanoma cells with or without BEL β-trefoil." (PMID 32168858, 2020). "However, for the first time, we demonstrated that a reciprocal activation between the RUNX2 and AKT/ERK pathways occurs in melanoma." (PMID 32204402, 2020). "For melanoma samples without TERT promoter mutation, we predicted HMGA2, HIF1, RUNX2 and TAL1 as the most significant regulators." (PMID 31888467, 2019). "Reduced levels of the receptor tyrosine kinases IGF-1R, FGFR1, PDGFRβ, and EGFR were detected in the RUNX2 knocked down 1205LU melanoma cells as compared with the non-silencing (control) ShRNA-expressing 1205LU cells." (PMID 27102439, 2016). "It is possible that the effect of RUNX2 on IGF1R protein expression does not occur at the transcriptional effect in 1205LU melanoma cells." (PMID 27102439, 2016). "Taken together, our results strongly suggest that RUNX2 might be a key player in RTK-based autocrine loops and a mediator of resistance to BRAF V600E inhibitors involving RTK up regulation in melanoma." (PMID 27102439, 2016). "Finally, we showed a dramatic up regulation of RUNX2 expression with concomitant up-regulation of EGFR, IGF-1R and AXL in melanoma cells resistant to the BRAF V600E inhibitor PLX4720." (PMID 27102439, 2016). "In addition, we found co-expression of RUNX2 and another RTK, AXL, in both melanoma cells and melanoma patient samples." (PMID 27102439, 2016). "We did not detect changes in the expression of FGFR1 in any of the RUNX2-knocked down melanoma cell lines (data not shown)." (PMID 27102439, 2016). "Thus, RUNX2 and CXCR4 represent two crucial molecules involved in melanoma progression." (PMID 38474372, 2024). "Furthermore, our results strongly suggest that RUNX2 might be a mediator of resistance to BRAF V600E targeted therapy, involving RTK up-regulation and activation in melanoma." (PMID 27102439, 2016). "The fluid circuit contained 3.8 mL of circulating medium with melanoma cells (MELHO, 1F5, or 1F5/RUNX2++ with or without WZ811), at a velocity of 0.3 cm/s, to simulate capillary flow." (PMID 38474372, 2024). "In fact, by treating WT melanoma cells with AKT or ERK inhibitors, we observed reduced activity of RUNX2, although RUNX2 gene expression was not affected." (PMID 32204402, 2020).
melanoma (continued). "However, by using parental and RUNT KO melanoma cells, both expressing similar FBXW11 and beta‐catenin levels, we observed that RUNT domain is able to prevent proteasome degradation of RUNX2 regardless of the expression of FBXW11." (PMID 37199076, 2023). "Due to that, we observed lower standard deviation and, thus, statistically significant differences in the level of MMP2, MMP14, RUNX2, or CD44 in CAFs obtained by incubation with conditioned media, but not by co-culturing with melanoma cells present on Transwell inserts." (PMID 35538545, 2022). "To determine whether RUNX2 expression played a role in sensitivity to PLX4720, we treated 1205LU melanoma cells expressing non-silencing ShRNA, ShRUNX2-2 or ShRUNX2-3 with 10 μM PLX4720 for 72 hours and counted viable cells." (PMID 27102439, 2016).
myeloma (37 papers, 2013 to 2025). "Though increased RUNX2 expression is associated with various B cell-derived malignancies, including myeloma, B-cell lymphoma and acute lymphoblastic leukemia, evidence for RUNX2 role in TIBs is lacking." (PMID 40990023, 2025). "RUNX2 deficiency can attract myeloma cells and promote myeloma development at new bone sites by secreting metastatic cytokines and suppressing bone marrow immunity." (PMID 37519798, 2023). "In this paper, we address the mechanisms associated with XRK3F2-mediated Runx2 derepression in myeloma-exposed preOB." (PMID 30008697, 2018). "In vivo, RUNX2 expression was positively correlated with bone loss in myeloma-bearing mice." (PMID 36897488, 2023). "The results suggest that myeloma cells with upregulated RUNX2 not only inhibit the proliferation and differentiation of osteoblasts but also promote the differentiation of osteoblasts to osteoclasts, which indirectly suppresses osteoclast activity." (PMID 36897488, 2023). "In an analysis of publicly available data, RUNX2 displayed elevated expression in myeloma plasma cells and was positively correlated with disease progression and unfavorable overall survival in patients." (PMID 36897488, 2023). "In vitro, conditioned medium from RUNX2-overexpressing myeloma cells reduced osteoblast activity and increased osteoclast activity." (PMID 36897488, 2023). "By observing the induction effects of conditioned medium from myeloma cells on preosteoblasts (MC3T3-E1) and preosteoclasts (RAW264.7) and constructing myeloma-bearing mice, we found that RUNX2 promotes bone destruction in multiple myeloma." (PMID 36897488, 2023). "RNA-sequencing analysis suggested communication between RUNX2, M-CSF, ITGB3, CD44, LCN2, and CLU in RUNX2 k/in myeloma cells." (PMID 36897488, 2023). "In a study of multiple myeloma, DNA binding activity and induction of osteopontin expression by RUNX2 were reported, which contributed to the proangiogenic effect of RPMI-8226 cells in vitro." (PMID 37108164, 2023). "In conclusion, we propose that upregulated RUNX2 promotes the suppression of osteoblast activity and enhancement of osteoclast activity by myeloma cells." (PMID 36897488, 2023). "We demonstrate that RUNX2 promotes the suppression of osteoblast activity and enhancement of osteoclast activity by multiple myeloma cells using in vitro and in vivo approaches." (PMID 36897488, 2023). "Western blot analysis indicated that MSCs RUNX2 proteins levels are lower treated with myeloma cells exosomes as compared to untreated cells or healthy plasma cell exosomes treated cells." (PMID 36451863, 2022). "Proof of Gfi1-mediated chromatin’s suppression of RUNX2 in the ambit of myeloma suppression derived from the demonstration that the boost of Gfi1 in preOBs blocked RUNX2 reporter expression." (PMID 35681577, 2022). "Further, RUNX2 has been demonstrated to play a role in T-cell lymphoma, acute myeloid leukemia, and multiple myeloma and to facilitate the response to viral infection through the control of Interferon Regulatory Factor 7 (IRF7)." (PMID 35886938, 2022). "Co-cultures of human myeloma cells with mesenchymal cells showed an inhibitory effect on osteoblast formation and reduced expression of Runx2/CBFA1 by mesenchymal cells has been found after coming in direct contact with myeloma cells." (PMID 34201396, 2021). "To verify our heparanase ChIP assay specificity, we probed the promoter region of the RUNX2 gene, known to promote myeloma progression." (PMID 32899927, 2020). "The role of Runx2 in MM-induced osteoblast inhibition has been demonstrated in coculture systems performed between myeloma cells and osteoprogenitor cells." (PMID 26579531, 2015). "MM-induced Runx2 inhibition in the osteoprogenitor cells is mediated by the cell-to-cell contact between myeloma and osteoprogenitor cells." (PMID 26579531, 2015). "Further study revealed that blocking RUNX2 in myeloma cells suppressed osteolytic lesions in vivo." (PMID 36897488, 2023).
myeloma (continued). "It has been confirmed that RUNX2 upregulation in myeloma cells aggravates bone destruction in vivo." (PMID 36897488, 2023). "In MM, RUNX2 derived from myeloma cells facilitates tumor development through Akt/β-catenin/survivin signaling and upregulates the expression of multiple metastasis-related genes, which might be responsible for myeloma bone resorption." (PMID 36897488, 2023). "Myeloma-bearing mice were constructed by tibia injection with control and RUNX2 k/in 5TGM1." (PMID 36897488, 2023). "Besides, we found a strong positive correlation between the levels of miR-92a-2-5p or miR-373-3p with NFATc1 mRNA, and a strong negative correlation between the levels of miR-373-3p with osterix (RUNX2 target gene) mRNA in myeloma patients." (PMID 36451863, 2022). "IL7 is mainly produced by MM cells and may directly diminish Runx2 transcriptional activity, reinforcing the adhesion-mediated inhibitory effect of myeloma cells on MSCs/pre-OBs." (PMID 34067236, 2021). "Cell to cell interactions of human myeloma cells and BMMSCs or pre-OBs were shown to inhibit OB formation and function via blockade of Runx2 activity, which was accompanied by a diminished expression of OB differentiation markers (i.e., ALP, osteocalcin, and collagen I)." (PMID 34067236, 2021). "Furthermore, we validated differentially methylated genes with osteogenic roles in the myeloma context, including RUNX2 and IBSP." (PMID 33462210, 2021). "Furthermore, the transcription factor RUNX2 and the secreted factor osteocalcin were markedly under-expressed in cells derived from myeloma patients." (PMID 31083455, 2019). "Importantly, it was determined that bone metastatic multiple myeloma cells induce epigenetic changes at the RUNX2 locus which prevent osteoblasts from differentiating." (PMID 29867053, 2018). "Interestingly, in the myeloma context, Gfi1 has recently been pointed out as a new transcriptional repressor of Runx2, blocking OB differentiation and being increased both in MSCs from MM patients and MM-bearing mice." (PMID 25268740, 2014). "Moreover, RUNX2 suppresses antitumor immunity in multiple myeloma cells." (PMID 35665333, 2022). "In addition, preclinical in vivo studies using genetically modified C57BL6/KaLwRij mice with RUNX family transcription factor 2 (RUNX2) deficient osteoblasts indicate that RUNX2 deficiency in MM osteoblasts, triggers myeloma cells and enhances myeloma dissemination and growth." (PMID 35847862, 2022). "According to the research results of cell type-specific regulatory activity, the most activated TFs in these myeloma cell subgroups included ETV7(C0 GNB2L1+ NK cells), TAF1(C1 RACK1+ NK cells), POU2F2(C2 HNRNPH1+ NK cells), and RUNX2(C3 ATP5E+ NK cells)." (PMID 40454289, 2025). "LncRNA RUNX2-AS1 in myeloma cells packed into exosomes can transfer to mesenchymal stem cells (MSCs) and inhibit osteogenic differentiation in an EV-mediated lncRUNX2-AS1/Runx2-dependent manner." (PMID 38495881, 2024). "Cell-to-cell contact between VLA-4 on myeloma cells and VCAM-1 on osteoblast progenitors suppresses Runt-related transcription factor 2 (RUNX2)/core binding factor-α1 (CBFA1)-mediated transcription and inhibits osteoblast formation." (PMID 38002311, 2023). "These experiments demonstrate that myeloma cells hnRNPA2B1 regulated monocytes IRF8 and NFATc1 or MSCs RUNX2 expression through exosomes miR-92a-2-5p or miR-373-3p." (PMID 36451863, 2022). "However, multiple intercellular cross-talk of MSCs with myeloma cells or other cells in the BMmilieu (through cell contact, soluble factors, or extracellular vesicles) deregulate the commented pathways or finally affect Runx2 activity, greatly influencing the osteogenic capacity of MSCs." (PMID 34067236, 2021). "Interactions via VLA-4 on myeloma cells and VCAM1 on MSCs were found partially responsible for this effect since antibodies blocking VLA-4 blunted the inhibitory effect on Runx2 activity." (PMID 34067236, 2021).
myeloma (continued). "Knockdown of GFI1 in multiple myeloma cells was sufficient to reverse the recruitment of EZH2 and HDAC1, increase RUNX2 expression, and rescue osteoblast differentiation." (PMID 29867053, 2018). "Some of these TFs were specifically downregulated in MSCs of active myeloma (RUNX2 and TEAD2), others were already downregulated in precursor myeloma stages (HOXC9 and CEBPD), whereas other TFs, including HOXA2 and ATF3, did not change their expression in any myeloma stages." (PMID 33462210, 2021). "In the same study, bone marrow biopsy specimens of myeloma patients with osteolytic lesions showed a markedly reduced number of Runx2/CBFA1 positive cells compared to those without myeloma bone disease." (PMID 34201396, 2021). "In contrast, human myeloma cells only block Runx2 activity, without modifying Runx2 expression in coculture system with a mesenchymal/stromal cell line." (PMID 26339248, 2015). "Runx2/CBFA1 is part of the non-canonical Wnt signaling pathway and constitutes a critical regulator of osteoblastogenesis, but this may also be affected by myeloma cells." (PMID 34201396, 2021). "In rescue experiments, in which the myeloma-induced repressive chromatin structure was already established on the Runx2 gene in preOB before addition of XRK3F2, we found that XRK3F2 can reverse the established epigenetic Runx2 suppression and alleviate this block to osteogenic differentiation." (PMID 30008697, 2018). "Indeed, these latter cells cocultured with the two HMCLs express less RUNX2 and COLLI amount in favor of the hypothesis that the modulation of CD99 by myeloma cells, in addition to other mechanism(s), could take part in the induction of a less differentiated OB phenotype." (PMID 26000312, 2015).